FAM216A (family with sequence similarity 216 member A)
Synonyms: C12orf24; HSU79274
Tractability: PROTAC: ubiquitination databases record sites on it.
Gene: Protein-coding gene on chromosome 12 (110,468,411 to 110,492,196, forward strand). Ensembl gene ENSG00000204856.
Subcellular location (Human Protein Atlas): Actin filaments
Genetic constraint (gnomAD): Loss-of-function variants: 16 observed, 21.07 expected, observed/expected ratio (o/e) 0.76, 90% interval 0.51 to 1.15. The upper end of that interval is the gene's LOEUF score, 1.15, which puts it in group 5 of 6, group 1 being the genes least tolerant of losing a copy. Missense variants: 240 observed, 217.61 expected, observed/expected ratio (o/e) 1.1, 90% interval 0.99 to 1.23. Synonymous variants: 77 observed, 77.37 expected, observed/expected ratio (o/e) 1, 90% interval 0.83 to 1.2.
Homologues: Orthologues: chimpanzee FAM216A (99% identical), macaque FAM216A (90% identical), guinea pig FAM216A (79% identical), pig FAM216A (77% identical), mouse Fam216a (63% identical), rat Fam216a (62% identical), rabbit FAM216A (60% identical), dog FAM216A (51% identical). Paralogues in human: FAM216B (13% identical).